CHRDL1 (chordin like 1)
Diseases named in the same sentence as CHRDL1 in open-access papers (continued):
Sharing a sentence is not in itself a finding about the gene and the disease.
cancer (continued). "The specific role of CHRDL1 in cancers should be further explored." (PMID 35494000, 2022). "The positive cancer status was correlated with lower CHRDL1 expression(P=0.006)." (PMID 35021154, 2022). "We found that CHRDL1 was significantly decreased in the majority of cancers." (PMID 35021154, 2022). "This suggested that CHRDL1 could predict patients who will be more conductive to anti-cancer therapy." (PMID 35021154, 2022). "CHRDL1 was observed to be notably downregulated in many cancers." (PMID 33980221, 2021). "There are three lncRNAs located close together in the interaction network: NONMMUG034109, NONMMUG021221, and NONMMUG008287; these are involved in the regulation of the mRNA expression of a large number of cancer-related genes, such as Pik3r1, Gulp1, Chrdl1, and Crebaf." (PMID 31947603, 2020). "Besides, CHRDL1 may be involved in some signal pathway related to the cancer development and immune response, which indicated CHARDL1 may be a potential target of treatment." (PMID 36749222, 2023). "Furthermore, the results of KEGG pathway enrichment analysis further demonstrated that CHRDL1 and its co-expressed genes were enriched in the pathway in cancer, phosphatidylinositol 3-kinase (PI3K)-AKT signaling pathway, cytokine-cytokine receptor interaction, focal adhesion and others." (PMID 36749222, 2023). "The results suggested that the expression levels of HLF, CHRDL1, and SELENBP1 in cancer tissues were significantly lower than those in normal tissues (p < 0.05)." (PMID 35205284, 2022). "One factor that has been shown recently to be overexpressed in cancers, including GBM, is the secreted BMP4 antagonist CHRDL1." (PMID 36497175, 2022). "And in pan-cancer patients, there was no substantial variance in DFS, DSS, OS and PFS between patients with CHRDL1 mutation and those without (p > 0.05)." (PMID 40230414, 2025). "CHRDL1, also known as Chordin-like 1, is an antagonist of bone morphogenetic proteins (BMPs), and BMP signaling involve in several physiological and pathological processes, including cell proliferation, migration and invasion in malignant tumor." (PMID 36776317, 2023). "CHRDL1, namely, Chordin Like 1, is a specific antagonist of bone morphogenetic protein (BMP), and BMP signaling participates in many responses, including cell proliferation, migration and invasion in various cancers." (PMID 33980221, 2021). "With respect to the genes having interaction(s) with miRNAs, we realized four down-regulated vDEGs (TMEM100, MYH11, CHRDL1, and FAM107A) to the accompaniment of five up-regulated vDEGs (KLK10, CLDN1, SLC6A6, MMP11, and SLC7A5) being documented by the GEPIA in both COAD and READ cancer types." (PMID 35333898, 2022). "For example, CHRDL1 may play a role in regulating angiogenesis but has not been reported to be related to cancer." (PMID 21060876, 2010). "Other predicted blood-secretory marker proteins such as PAICS, CHRDL1, KLF2, COL10A1 and MYL9 have not heretofore been reported to be cancer related." (PMID 21060876, 2010).
adenocarcinoma (1 paper, 2025). A common cancer characterized by the presence of malignant glandular cells. "Immunohistochemical assays were performed on tissue specimens from patients with LUAD, revealing significantly higher CHRDL1 expression in normal tissues compared to adenocarcinoma tissues." (PMID 40230414, 2025).
metabolic disease (1 paper, 2015). A congenital disorder (due to inherited enzyme abnormality) or acquired (due to failure of a metabolically important organ) disorder resulting from an abnormal metabolic process. "The results supported the hypothesis that CTEPH is a metabolic disease as the mRNA expression level of oxidized low-density lipoprotein receptor 1 showed the greatest upregulation, while the mRNA expression level of chordin-like 1 showed the greatest downregulation." (PMID 25522749, 2015).
CHRDL1 also shares sentences with these, for which no sentence is quoted: acute myeloid leukemia (2 papers); colorectal cancer (2); lung squamous cell carcinoma (2); acute lymphoblastic leukemia (1); amyotrophic lateral sclerosis (1); bladder urothelial carcinoma (1); brittle cornea syndrome (1); cardiac hypertrophy (1); cataract (1); cervical squamous cell carcinoma (1); clear cell renal carcinoma (1); colon adenocarcinoma (1); colorectal adenoma (1); connective tissue disorder (1); corneal dystrophy (1); corneal oedema (1); developmental delay (1); Ehlers-Danlos syndrome (1); glioblastoma (1); hepatocellular carcinoma (1); Huntington disease (1); infection (1); meningioma (1); mesothelioma (1); myocardial infarction (1); neurodegenerative disease (1); non-small cell lung carcinoma (1); osteoporosis (1); primary congenital glaucoma (1); prostate tumors (1).
A further 5 diseases each share a sentence with CHRDL1 in 1 paper.